BCRP1 (BCR pseudogene 1)
Synonyms: BCR-1
Gene: Transcribed unprocessed pseudogene on chromosome 22 (24,259,929 to 24,263,764, reverse strand). Ensembl gene ENSG00000225098.
Diseases named in the same sentence as BCRP1 in open-access papers:
BCRP1 is named in the same sentence as 15 diseases in open-access papers, as found by Europe PMC text mining. Sharing a sentence is not in itself a finding about the gene and the disease. The quoted sentences say what the papers report.
breast cancer (6 papers, 2006 to 2024). A primary or metastatic malignant neoplasm involving the breast. "P-gp, MRP1, and BCRP1 are widely used by breast cancer cells to pump anticancer agents out of the breast cancer cells and are targets of breast cancer therapeutic research." (PMID 38543147, 2024). "BCRP1 accounts for chemoresistance of some clinical cancers including acute myeloid leukemia, non-small cell cancer, and breast cancer." (PMID 17140455, 2006). "Long-term exposure to PARP inhibitor Olaparib has been shown to induce the overexpression of MDR1 and BCRP1, leading to drug resistance in mouse mammary tumours, that could be reversed by pharmacological inhibition or deletion of MDR1." (PMID 36819096, 2023). "In the study by Britton and colleagues with both clinical fine needle aspirates obtained from breast cancer patients as well as established breast cancer cell lines, the expression of ATP-binding cassette sub-family G member 2 (ABCG2=BCRP1) was monitored." (PMID 25051360, 2014).
ovarian carcinoma (4 papers, 2010 to 2022). A malignant neoplasm originating from the surface ovarian epithelium. "A side population of cells expressing NANOG, OCT4 and ABCG2/BCRP1 was isolated from ovarian cancer cell lines and ascites of ovarian cancer patients, and was found to have increased tumourgenicity and chemoresistance." (PMID 34283069, 2021). "The ABC transporter protein ABCG2/BCRP1 has alsobeen shown to have a high expression in ovarian cancer cells found within theascites." (PMID 31069311, 2018). "ABCG2/BCRP1 expression was also found in human ovarian cancer cells from patient ascites and was expressed in SP cells more extensively than in non-SP cells." (PMID 20354527, 2010). "Our study shows that ovarian cancer SP cells express the embryonic stem cell markers, NANOG, OCT4, STELLAR, and ABCG2/BCRP1." (PMID 20354527, 2010). "In addition to ABCG2/BCRP1, many embryonic stem cell markers, such as NANOG, OCT4 and STELLAR, were expressed in SP cells of ovarian cancer." (PMID 35982417, 2022). "Stem cell markers NANOG and ABCG2/BCRP1 were colocalised in both SP and non-SP cells, and the specific individual cells in ovarian cancer tissues, as illustrated in our study, make it reasonable to hypothesise that there are cancer stem-like cell niches in ovarian cancer." (PMID 20354527, 2010).
glioma (3 papers, 2013 to 2022). A benign or malignant brain and spinal cord tumor that arises from glial cells (astrocytes, oligodendrocytes, ependymal cells). "At the predicted molecular weight, BCRP1 was only detected in one of our pediatric glioma cultures, although additional bands of higher molecular weight were detected in half of the cultures, suggesting the formation of oligomers." (PMID 23637844, 2013). "There are higher levels of P-gp and BCRP1 in the endothelial cells of the tumor vasculature than in the glioma cells themselves, which is in line with findings in adult glioma." (PMID 23637844, 2013). "More precisely, we determined the expression of three major drug efflux transporters present in brain: P-glycoprotein/MDR1 (P-gp), Multidrug Resistant Protein 1 (MRP1), and Breast Cancer Resistance Protein 1 (BCRP1), on both the glioma cells and surrounding tissue." (PMID 23637844, 2013). "In children aged from 1 week to 11 years with high-grade glioma, tumor-tissue staining indicated the presence of P-gp, MRP1, and BCRP1 on the tumor vasculature, while MRP1 is also expressed in glioma cells." (PMID 36015138, 2022). "The correlation of MGMT, BCRP1, and A2B5 expression with prognosis of glioma patients was investigated through Kaplan–Meier survival curve analysis with a log-rank test of 50 GBM patients." (PMID 33562724, 2021). "Immunohistochemical staining on the corresponding tumor tissue indicates the presence of P-gp, MRP1, and BCRP1 on the tumor vasculature, while only MRP1 is also expressed in glioma cells." (PMID 23637844, 2013). "We subsequently determined the expression of the drug efflux transporters P-gp, BCRP1, and MRP1 in glioma cultures and their corresponding tumor tissues." (PMID 23637844, 2013). "Results indicate the presence of P-gp, MRP1 and BCRP1 in the tumor vasculature, and expression of MRP1 in the glioma cells themselves." (PMID 23637844, 2013). "The absence of BCRP1 on glioma cells that was observed on Western blot, corresponded with the immunohistochemistry results." (PMID 23637844, 2013). "Staining of BCRP1 in glioma cells was mostly negative or weak, while the microvasculature showed intense staining in the majority of the sections." (PMID 23637844, 2013). "Moreover, it has been demonstrated that BCRP1 function not only correlates with high stem cell (SC) marker expression and self-renewal capacity but can also actively drive these SC features in some GBM cultures without regulating glioma cell tumorigenicity or radiation resistance." (PMID 33562724, 2021).
brain tumor (1 paper, 2016). "Importantly, recent work has shown that dasatinib (or other TKI) delivery to brain tumor parenchyma may be further improved by strategies to inhibit active efflux proteins (P-glycoprotein (P-gp) and breast cancer resistance protein (Bcrp1))." (PMID 27582545, 2016).
ischemic stroke (1 paper, 2021). A stroke disorder caused by obstruction of blood flow to the brain, due to thrombotic (local blood clot formation) or embolic (due to a blood clot or other material traveling from another site) event. "Future work may include functional assessment of BCRP1, which was shown to be upregulated in the NVU on-a-chip model compared to 2D, and GLUT-1, which is reported to become upregulated following ischemic stroke." (PMID 34906183, 2021).
tumor (13 papers, 2006 to 2024). "It has been shown that administration of antiestrogen drugs intensifies the anti-tumor activity of cisplatin, and progesterone activates the expression of a key multidrug resistance gene—BCRP1." (PMID 37569668, 2023). "Western blot analysis revealed that expressions of MDR phenotype (MDR1, MRP1, BCRP1) was increased with the elevated tumor grades, and more interestingly, with CTGF upregulation." (PMID 28617438, 2017). "In the present study, the cancer stem-like cells from tumor spheres were more resistant to cisplatin and epirubicin and exhibited a higher invasive potential than the Bcrp1-positive cervical CSCs." (PMID 24676900, 2014). "ABCG2/BCRP1 is a transmembrane protein that plays an important role in the multidrug resistance (MDR) of tumor cells." (PMID 24418020, 2014). "In all patient samples BCRP1 is intensely expressed in the endothelial cells of the tumor vasculature, as also seen in endothelial cells of normal brain, but hardly on the tumor cells themselves." (PMID 23637844, 2013). "The ABCG2/BCRP1 gene was first isolated from human tumour cell lines, in which it was involved in drug resistance." (PMID 20354527, 2010). "BCRP1 has been demonstrated to play an important role in the drug resistance of normal stem cells and tumor stem cells." (PMID 17140455, 2006). "BCRP1 over-expressing tumor cells, however, are only resistant to mitoxantrone, adriamycin, daunorubicin, etoposide, topotecan, and irinotecan." (PMID 17140455, 2006). "Despite evidence of anti-tumor efficacy in the brains of wild-type mice, Milciclib delivery can be enhanced into the brain in MDR1a/b and BCRP1 triple-knockout mice, suggesting that the anti-tumor efficacy of Milciclib in brain tumors can be enhanced by the regulation of ABC transporter activity." (PMID 38786013, 2024). "High expression of ABCG2/BCRP1 in SP cells is contributed to drug resistance and tumor recurrence." (PMID 24418020, 2014). "Immunohistochemistry scores of P-gp, Mrp1, and Bcrp1 in tumor tissue sections." (PMID 23637844, 2013). "ABCG2/BCRP1 (breast cancer-resistance protein-1), an ATP-binding cassette (ABC) transporter, is a cell surface drug-resistance marker as well, which has been used to identify stem cells from a variety of tissues, including tumours." (PMID 20354527, 2010). "However BCRP1, MDR3 and MRP1 were upregulated in tumours versus control tissues." (PMID 28061436, 2017). "Due to the great histological complexity of the tumor and the PT tissue, we performed an unbiased stereometric analysis of histological samples by evaluating the cell density of both positive and negative cells for MGMT, BCRP1, and A2B5, as described in the Materials and Methods section." (PMID 33562724, 2021).
cancer (8 papers, 2006 to 2023). A tumor composed of atypical neoplastic, often pleomorphic cells that invade other tissues. "Four different epitopes, previously related to cancer stem cells, were analyzed: BCRP1, EpCam, CD133, and AC133." (PMID 38001682, 2023). "The phenotype of SP cells is characterized by high expression of breast cancer-resistant protein-1 (BCRP1 or ABCG2), one of ATP-binding cassette (ABC) transporters, which is associated with multidrug resistance in many cancers by pumping out the drugs." (PMID 25951238, 2015). "Consistent with this, a cancer stem-cells cell line (WJ2) derived from GBM showed increased expression of BCRP1, CD133 and the neural precursor marker Nestin and at the same time maintained Wnt-1 expression." (PMID 22400111, 2012). "Therefore, ABCG2/BCRP1 expression is a useful marker for positive selection of several types of cancer stem-like cells." (PMID 20354527, 2010). "Therefore, we proposed that both anti-apoptosis factors and BCRP1 contribute the drug resistant property on CD133 positive cancer stem cells." (PMID 17140455, 2006). "Xuan and Hu reported that Shikonin derivatives circumvented diverse cancer drug resistance (P-gp, MRP1, BCRP1, Bcl-2, Bcl-xL) by inducing a dominant necrosis." (PMID 19594888, 2009). "Specifically, BCRP1/ABCG2, an ABC transporter, has been shown to play a major role in development of the SP phenotype in stem and progenitor cells during murine hematopoiesis and spermatogenesis and in human cancer stem-like cells." (PMID 35334216, 2022). "BCRP1 and MDR1 ABC transporters allow the exclusion of Hoechst 33342 dye, a feature that defines the pluripotential side population (SP) originally reported in haematopoietic stem cells and now used to identify cancer stem cells." (PMID 22400111, 2012). "Taken together, because of higher BCRP1, MGMT and IAPs levels, CD133 positive cancer stem cells may be resistant to conventional chemotherapy and contribute to disease relapse." (PMID 17140455, 2006).
BCRP1 also shares sentences with these, for which no sentence is quoted: glioblastoma (2 papers); acute myeloid leukemia (1); kidney cancer (1); leukemia (1); osteosarcoma (1); ovarian adenocarcinoma (1); pancreatic cystadenoma (1); papillary adenoma (1).